TLR10 (toll like receptor 10)
Description:
Participates in the innate immune response to microbial agents. Acts via MYD88 and TRAF6, leading to NF-kappa-B activation, cytokine secretion and the inflammatory response (By similarity).
Synonyms: CD290
Tractability: Small molecule: it has a binding pocket of medium quality; it belongs to a druggable protein family. Antibody: its Gene Ontology location is reachable by antibodies, with high confidence; UniProt predicts a signal peptide or a membrane-spanning region; the Human Protein Atlas places it where antibodies can reach. PROTAC: ubiquitination databases record sites on it.
Gene: Protein-coding gene on chromosome 4 (38,772,238 to 38,782,990, reverse strand). Ensembl gene ENSG00000174123.
Subcellular location: Membrane
Subcellular location (Human Protein Atlas): Plasma membrane; Endoplasmic reticulum
Pathways (Reactome):
Immune System: MyD88 cascade initiated on plasma membrane; Toll Like Receptor 10 (TLR10) Cascade
Disease: IRAK4 deficiency (TLR5)
Gene Ontology:
Molecular function: identical protein binding; protein binding; lipopeptide binding; signaling receptor activity; Toll-like receptor 2 binding; transmembrane signaling receptor activity
Biological process: cellular response to bacterial lipopeptide; immune response; inflammatory response; innate immune response; toll-like receptor signaling pathway; signal transduction
Cellular component: receptor complex; membrane; plasma membrane
Genetic constraint (gnomAD): Loss-of-function variants: 2 observed, 2.39 expected, observed/expected ratio (o/e) 0.84, 90% interval 0.32 to 1.83. That is too few expected variants to judge how well the gene tolerates losing a copy. Missense variants: 929 observed, 964.68 expected, observed/expected ratio (o/e) 0.96, 90% interval 0.91 to 1.02. Synonymous variants: 287 observed, 351.13 expected, observed/expected ratio (o/e) 0.82, 90% interval 0.74 to 0.9.
Homologues: Orthologues: chimpanzee TLR10 (99% identical), macaque TLR10 (97% identical), pig TLR10 (81% identical), rabbit TLR10 (76% identical), guinea pig TLR10 (74% identical), rat Tlr10 (71% identical). Paralogues in human: TLR1 (47% identical), TLR6 (47% identical), TLR2 (28% identical), TLR8 (22% identical), TLR3 (21% identical), TLR7 (19% identical), TLR5 (19% identical), TLR4 (18% identical), LRRC32 (14% identical), RXFP1 (14% identical), CD180 (14% identical), NRROS (13% identical), and 10 more.
Diseases named in the same sentence as TLR10 in open-access papers:
TLR10 is named in the same sentence as 84 diseases in open-access papers, as found by Europe PMC text mining. Sharing a sentence is not in itself a finding about the gene and the disease. The quoted sentences say what the papers report.
asthma (22 papers, 2009 to 2025). "TLR9 and TLR10 were linked to better asthma control and improved cardiac function, while subclinical left and right ventricular dysfunction was observed in asthmatic children." (PMID 40218167, 2025). "The CC genotype of TLR9 and the GG genotype of TLR10 are associated with better asthma control and better cardiac function." (PMID 40218167, 2025). "Single nucleotide polymorphisms (SNP) in five different TLRs (TLR2, TLR4, TLR6, TLR9, TLR10) were described to significantly contribute to asthma susceptibility, severity, and responsiveness." (PMID 37759430, 2023). "Patients with ACO are characterized by an enhanced expression of several genes, such as toll-like receptor 10 (TLR10) which has been previously implicated in the pathogenesis of the asthma." (PMID 35330379, 2022). "In Mendelian randomization, the blood expression of TLR10 was positively associated with the risk of asthma (PIVW = 4.34E−6)." (PMID 34103634, 2021). "The genetic variation in TLR10 rs4129009, which was also determined in the present study, was associated with asthma risk in two independent samples from the USA26." (PMID 28592890, 2017). "Current asthma was more common (30%) in children with the variant AG or GG genotype in the TLR10 rs4129009 gene versus those who were homozygous for the major allele A (11%) (p = 0.03)." (PMID 28592890, 2017). "Our finding that the TLR10 gene polymorphism was associated with current asthma is in accordance with these observations." (PMID 28592890, 2017). "In conclusion, polymorphism in the TLR10 gene seems to increase the risk of post-bronchiolitis asthma in preschool-aged children, and polymorphism in the TLR7 gene seems to increase the risk of post-bronchiolitis asthma in preschool-aged girls." (PMID 28592890, 2017). "Previous genetic studies have associated TLR10 with inflammatory diseases such as asthma, Crohn's disease and Ménière's disease, that is suspected to have autoimmune properties." (PMID 26442097, 2015). "It has been shown that the T allele of the rs2381289 single nucleotide polymorphism (SNP) in TLR6 contributes to the development of allergic rhinitis and asthma, while the A allele of rs11466651 SNP in TLR10 is negatively associated with asthma development." (PMID 26617525, 2015). "Genetic variations in TLR1, TLR2, TLR4, TLR6 and TLR10 have been associated with the development of asthma." (PMID 24524443, 2014). "Haplotype spanning of polymorphisms in TLR6 and TLR10 (see TLR10) revealed an association with childhood asthma, indicating no individual but a combined influence of these polymorphisms on asthma in children." (PMID 23496969, 2013). "For TLR10, out of the eight studied polymorphisms, rs4129009 and rs11096957 showed association with (atopic) asthma in some studies." (PMID 23496969, 2013). "Genetic variation in TLR2, TLR4, TLR10 and TLR1TLR6 and TLR10 have been associated with the development of asthma, and in TLR9 a promoter polymorphism has been associated with atopic eczema." (PMID 22857391, 2012). "TLR10 single nucleotide polymorphisms have also been associated with asthma in two independent samples although the ligand for TLR10 has not been defined." (PMID 21108806, 2010). "Resequencing of TLR10 in 47 subjects has identified most SNPs and suggested possible association of this gene with asthma." (PMID 19924287, 2009). "Specifically, the strongest remaining signal (P < 10−15) after using ACs surrounds rs5743618 on chromosome 4, linked to toll-like-receptor genes involved in innate immunity, including TLR1 and TLR10, one of the strongest hay fever hits in European GWAS cohorts, with weaker asthma risk association." (PMID 39901012, 2025). "The CC genotype of TLR9 and the GG genotype of TLR10 are associated with better asthma control." (PMID 40218167, 2025).
asthma (continued). "Although there is a lack of in-depth analysis of its biological function, genetic studies have found that the polymorphisms of the human TLR10 gene are associated with various disease states, including bacterial infections, asthma, autoimmune diseases, and cancer." (PMID 40672946, 2025). "Moreover, we investigated TLR9 (rs 187084) and TLR10 (rs 11096956) gene polymorphisms and their association with asthma." (PMID 40218167, 2025). "If a population was exposed to different environmental triggers (e.g., allergens, pollution, infections), TLR10 (rs11096956) might play a role in asthma susceptibility in the presence of specific environmental conditions." (PMID 40218167, 2025). "Furthermore, a polymorphism in the TLR6 gene contributed to the development of asthma and allergic rhinitis, whereas an SNP in the TLR10 gene was negatively associated with asthma development." (PMID 37759430, 2023). "Firstly, current asthma was more common in children who had the variant TLR10 rs4129009 genotype." (PMID 28592890, 2017). "The association of the TLR10 gene with asthma has been documented in European-American populations." (PMID 27498757, 2016). "TLR2, TLR6, TLR9, and TLR10 have been associated with asthma in several studies." (PMID 23496969, 2013). "However, it seems likely that TLR10 is functional because TLR10 gene variants have been associated with susceptibility to asthma." (PMID 23194300, 2012). "Therefore, the final analyses on the role of TLR10 rs4129009 were performed with multivariate logistic regression adjusted for age, sex, early-life risk factors, and current risk factors for asthma, including the RSV aetiology of early-life bronchiolitis, and the conclusions did not change." (PMID 28592890, 2017). "The present study was carried out to complement this exploratory study series by evaluating whether the TLR3 rs3775291, TLR4 rs4986790, TLR7 rs179008, TLR8 rs2407992, TLR9 rs187084, and TLR10 rs4129009 polymorphisms are associated with post-bronchiolitis asthma." (PMID 28592890, 2017). "Individuals with asthma have an increased expression of TLR1 and TLR10 in their airway epithelial cells compared to controls, suggesting these genes are asthma therapeutic targets." (PMID 39406500, 2024). "We found a strong colocalization signal between the blood eQTL for TLR10 and the GWAS for asthma (PP4 = 0.84)." (PMID 34103634, 2021). "TLR1, TLR2, TLR6, and TLR10 comprise the TLR2 subfamily, and TLR1, TLR2, TLR6, and TLR10 gene polymorphisms seem to play a role in susceptibility to asthma, atopic eczema, and allergic rhinitis." (PMID 28592890, 2017). "We also identified two missense mutations in TLR10, C-rs4129009 (p.Ile775Val) (PGWAS = 1.49E−10) and G-rs11096957 (p.Asn241His) (PGWAS = 2.49E−10), which are in moderate LD (r2 = 0.42 in CEU) and associated with the risk of asthma." (PMID 34103634, 2021). "One line of inquiry could examine the possibility that TLR10 dampens TLR2 signaling and IL6 production, thereby increasing the risk of asthma." (PMID 34103634, 2021). "Furthermore, it has been shown that genetic variations in TLR10 can lead to various ailments, such as Crohn's disease and asthma." (PMID 30930906, 2019). "We evaluated whether post-bronchiolitis asthma was associated with polymorphisms in the TLR3 rs3775291, TLR4 rs4986790, TLR7 rs179008, TLR8 rs2407992, TLR9 rs187084, and TLR10 rs4129009 genes." (PMID 28592890, 2017). "Polymorphism in the TLR10 gene increases and in the TLR7 gene may increase the risk of asthma in preschool-aged children after infant bronchiolitis." (PMID 28592890, 2017). "Therefore, TLR9 and TLR10 have a role in asthma control and cardiac dysfunction." (PMID 40218167, 2025). "Puthothu and Heinzmann, who involved 322 asthmatic children and 270 randomly selected controls to assess whether TLR6, TLR10, or both were involved in asthma genetics, found no individual association between TLR10 (rs11096956) and bronchial asthma." (PMID 40218167, 2025).
asthma (continued). "However, TLR10 genetic variants have not yet been associated with RA, but they have been associated with susceptibility to infectious and inflammatory diseases such as extrapulmonary tuberculosis and asthma." (PMID 27716427, 2016). "Although single nucleotide polymorphisms in the TLR10 gene have been associated with lung diseases, such as tuberculosis (rs11096957), bronchiolitis, asthma (rs4129009), and sarcoidosis (rs1109695), TLR10-mediated immune regulation in lung epithelial cells has not been studied." (PMID 36671404, 2022).
tuberculosis (8 papers, 2007 to 2025). A chronic, recurrent infection caused by the bacterium Mycobacterium tuberculosis. "Polymorphisms in the TLR10/1/6 gene cluster have been linked to incidence of several cancers, as well as tuberculosis and leprosy." (PMID 40694589, 2025). "Association between TLR10 tagSNPs and risk of TB and latent infection in the Chengdu latent tuberculosis infection cohort." (PMID 29527210, 2018). "In individuals with tuberculosis, the G/A (TLR6-rs5743810) and G/T (TLR10-rs11096957) genotypes have a significant association with a higher susceptibility to developing pulmonary tuberculosis (OR = 2.48, 95% CI 1.62–3.85)." (PMID 37888601, 2023). "In support of this hypothesis, the TLRs are upregulated as a group in both melioidosis (TLR1, TLR2, TLR4, TLR5, TLR6, TLR8 and TLR10) and tuberculosis (TLR2, TLR4, TLR5, TLR6, TLR7, TLR8)." (PMID 23383015, 2013). "Compared to control subjects, African American tuberculosis cases had a significantly increased frequency of rare NSPs in TLR1 (OR = 3.32; P = 0.002), TLR6 (OR = 1.85; P = 0.040), and TLR10 (OR = 1.76; P = 0.009)." (PMID 18091991, 2007). "There is evidence that TLR10, a TLR2 signaling modulator, may be involved in progression of tuberculosis (TB)." (PMID 29527210, 2018).
bronchiolitis (6 papers, 2016 to 2025). Inflammation of the bronchioles characterized by swelling of the bronchioles and mucus accumulation. "Our study was an exploratory study on the possible association between the TLR7 rs179008, TLR8 rs4207992, TLR9 rs187084 or TLR10 rs4219009 gene polymorphisms and characteristics of bronchiolitis in early infancy or post-bronchiolitis outcomes." (PMID 27498757, 2016). "In addition, an SNP in TLR-10, rs4129009, has been associated with preschool wheezing after an episode of bronchiolitis in infancy." (PMID 36362786, 2022). "TLR9 rs187084 gene polymorphism may be associated with post-bronchiolitis wheezing, and TLR10 rs4129009 gene polymorphism may be associated with atopy." (PMID 27498757, 2016). "The aim of the present study was to complement this exploratory study series by evaluating whether the TLR7 rs179008, TLR8 rs2407992, TLR9 rs187084 and TLR10 rs4129009 polymorphisms are associated with the presence, clinical characteristics and viral etiology of bronchiolitis in early infancy." (PMID 27498757, 2016). "The aim of this exploratory study was to evaluate whether there are associations between TLR7 rs179008, TLR8 rs2407992, TLR9 rs187084 or TLR10 rs4129009 polymorphisms and viral findings, clinical characteristics or subsequent wheezing in infants with bronchiolitis." (PMID 27498757, 2016). "The joint analyses of the TLR1 rs5743618, TLR2 rs5743708, TLR6 rs5743810 and TLR10 rs4129009 genotype combinations and baseline (z-scores) and hyper-reactivity IOS measurements (Δz-scores) in 97 children hospitalized for bronchiolitis." (PMID 26741133, 2016).
HIV-1 infection (4 papers, 2019 to 2024). The type species of lentivirus and the etiologic agent of acquired immunodeficiency syndrome (AIDS). "Whether TLR2 and TLR10 interact and associate with each other in the context of an HIV-1 infection remains unclear and will be intriguing to investigate in future studies." (PMID 30930906, 2019). "Additionally, TLR-10 has been associated with enhanced HIV-1 infection." (PMID 38397105, 2024). "A role of TLR10 in HIV-1 infection has recently been described, whereby HIV-1 gp41 was recognized as a TLR10 ligand, leading to the induction of IL-8 and NF-κBα activation." (PMID 37298575, 2023). "Together, these data indicate that the expression of TLR1, 2 and TLR10 alone or in combination significantly enhances HIV-1 infection and integration in vitro." (PMID 30930906, 2019). "The present investigation demonstrated that TLR10 acts as an innate immune sensor for HIV-1 infection and leads to the induction of IL-8." (PMID 30930906, 2019). "We believe that the data shown in the present study describing an HIV-1 ligand for TLR10 will advance our current knowledge, as well as further our understanding of the role of TLR10 in innate immunity during HIV-1 infection." (PMID 30930906, 2019). "We suggest that TLR10 and TLR1 both work cooperatively as the transfection of TRL10 and TLR1 alone or in combination significantly enhanced HIV-1 infection, indicating that TLR10 and TLR1 likely form heterodimers." (PMID 30930906, 2019). "To our knowledge, we are the first to report that TLR10 is involved in HIV-1 infection and most importantly, that gp41 acts as a ligand for TLR10 in human macrophages and MECs." (PMID 30930906, 2019). "In vitro studies using TZMbl cells demonstrated that TLR10 overexpression contributes to higher HIV-1 infection and proviral DNA integration." (PMID 30930906, 2019). "Although our current data demonstrates the involvement of TLR10 in HIV-1 infection, the existence of such synergy between TLR10 and TLR3 in an HIV-1 infection cannot be dismissed and requires further future investigation." (PMID 30930906, 2019). "The results showed a significantly increased rate of HIV-1 infection in TZMbl cells overexpressing TLR10 and heterodimers TLR1 or TLR2 compared to the empty vector alone, uninfected control or a T20 control (Enfuvirtide; HIV-1 fusion inhibitor) (P < 0.05)." (PMID 30930906, 2019). "In the present study, we sought to evaluate the level of TLR10 expression in breast milk (BM) and explore its potential function in the context of HIV-1 infection." (PMID 30930906, 2019). "In vitro studies using TZMbl cells demonstrated that TLR10 overexpression could enhance HIV-1 infection and proviral DNA integration." (PMID 37298575, 2023). "Next, we determined the extent of HIV-1 infection in TLR10 and TLR2 stable reporter cell lines." (PMID 30930906, 2019). "Taken together, our data reveal for the first time that TLR10 is involved in HIV-1 infection." (PMID 30930906, 2019). "Conversely, TLR10 inhibition significantly decreased HIV-1 infection." (PMID 30930906, 2019). "For this purpose, HIV-1 reporter TZMbl cells were transiently transfected alone or in combination with plasmids overexpressing TLR10 and the heterodimers, TLR2 and TLR1, followed by HIV-1 infection and measurement of luciferase activity." (PMID 30930906, 2019). "Therefore, it is highly likely that TLR2 and TLR10 are independently involved in the regulation of HIV-1 infection in a non-heterodimeric form." (PMID 30930906, 2019). "Given that TLR10 is a homolog of both TLR2 and TLR1, we hypothesized that TLR10 is involved in sensing specific HIV-1 structural proteins, which leads to increased cellular activation and HIV-1 infection." (PMID 30930906, 2019).
HIV-1 infection (continued). "Moreover, based on TLR10 and TLR2 co-transfection or co-depletion through siRNA and effect on HIV-1 infection or integration, TLR10 appears to play a role in HIV-1 infection and integration independent of TLR2 since no additive effect of TLR10 and TLR2 was observed." (PMID 30930906, 2019). "Surprisingly, with the exception of TLR1 and TLR2, we found significantly higher levels of TLR10 (>100-fold) expression in BM samples collected from HIV-1 infected Nigerian women, thus indicating that TLR10 might play an important role in HIV-1 infection and pathogenesis." (PMID 30930906, 2019).
leprosy (4 papers, 2018 to 2025). Leprosy is a chronic infectious disease affecting primarily the skin and peripheral nervous system. "Indoleamine 2,3-dioxygenase 1 (IDO1) expression alone was highly discriminatory, followed by TLR10, BLK, CD38, and SLAMF7, whereas the HS3ST2 and CD40LG mRNA separated multi- and paucibacillary leprosy." (PMID 34695167, 2021).
prostate carcinoma (4 papers, 2012 to 2021). A carcinoma that arises from epithelial cells of the prostate gland. "Sequence variants of TLR4 are associated with prostate cancer risk and sequence variants of TLR4 and TLR10 are associated with nasopharyngeal cancer risk." (PMID 22985132, 2012).
viral infection (4 papers, 2016 to 2024). "The interaction of vitamin D with TLR10 could potentially influence the body’s defense mechanisms against viral infections, including SARS-CoV-2." (PMID 39902041, 2024). "Several ligands as well as in response to bacterial and viral infections, have been described to elicit a TLR10-dependent response, however, no solid evidence has been provided so far to support what could be the true ligands of TLR10 for its sensing and signaling." (PMID 29616030, 2018).
breast carcinoma (3 papers, 2010 to 2026). "A recent study showed that TLR10 was upregulated, thus promoting immune infiltration in breast cancer, and played an important role in tumor development." (PMID 36387234, 2022).